HSP90AA2P (heat shock protein 90 alpha family class A member 2, pseudogene)
Description:
Putative molecular chaperone that may promote the maturation, structural maintenance and proper regulation of specific target proteins.
Synonyms: HSPCA; HSP90ALPHA; formerly HSPCAL3; HSP90AA2
Gene: Processed pseudogene on chromosome 11 (27,888,838 to 27,891,033, reverse strand). Ensembl gene ENSG00000224411.
Subcellular location: Cytoplasm
Diseases named in the same sentence as HSP90AA2P in open-access papers:
HSP90AA2P is named in the same sentence as 14 diseases in open-access papers, as found by Europe PMC text mining. Sharing a sentence is not in itself a finding about the gene and the disease. The quoted sentences say what the papers report.
liver cancer (1 paper, 2024). An epithelial or non-epithelial malignant neoplasm that arises from the liver. "In liver cancer, upregulated HSP90AA2P promotes cancer cell survival, proliferation, and stabilizes oncoproteins and signaling pathways associated with tumor progression." (PMID 39286634, 2024). "In the iCCA vs. CIR comparison, seven proteins showed higher abundance in the iCCA patient group, among which haptoglobin (HP), cAMP-dependent protein kinase catalytic subunit beta (PRKACB), heat shock protein (HSP) 90-alpha A2 (HSP90AA2P) were previously reported with respect to liver cancer." (PMID 39286634, 2024).
HSP90AA2P also shares sentences with these, for which no sentence is quoted: tumor (5 papers); cancer (4); breast carcinoma (1); colon cancer (1); gastrointestinal stromal tumor (1); immune diseases (1); invasive carcinoma (1); latent infection (1); leukemia (1); metastatic melanoma (1); prostate tumour (1); systemic lupus erythematosus (1); viral infection (1).